FGFR4 (fibroblast growth factor receptor 4)
Diseases named in the same sentence as FGFR4 in open-access papers (continued):
Sharing a sentence is not in itself a finding about the gene and the disease.
tumor (continued). "Notably, FGFR4 inhibitors also have direct effects on immune cells in the tumor microenvironment, such as myeloid-derived suppressor cells (MDSCs) and M2-type tumor associating macrophages (M2-TAMs)." (PMID 34576070, 2021). "In particular, we showed that the FGFR4 expression fluctuated with the genotypes of rs351855 in blood cells, implicating a differential impact of tumor-infiltrating immune cells on CRC progression according to distinct FGFR4 activation levels among patients of different rs351855 genotypes." (PMID 34071523, 2021). "Additionally, FGFR4 drives tumor cell proliferation by inhibiting apoptosis induced by stress-related MST1/2 signaling." (PMID 34724890, 2021). "Under these conditions, FGFR4 can potentiate cancer progression by modulating nuclear factor kappa B (NF-κB) and increasing the inflammatory microenvironment, thus entering in a loop that promotes tumor development." (PMID 34200439, 2021). "After multivariate adjustment for the known prognostic factors Ki-67 and ENSAT tumor stage, FGFR1 remained significantly associated with recurrence-free survival (HR=6.10, 95%CI: 1.78 – 20.86, p=0.004) and FGFR4 with overall survival (HR=3.23, 95%CI: 1.52 – 6.88, p=0.002)." (PMID 34956100, 2021). "The authors hypothesized that the tumor-suppressor function of FGFR4 could be the result of its co-expression with β-klotho." (PMID 34200439, 2021). "Primary HCC tissues consist of tumor cells with varying expression of FGF19/FGFR4." (PMID 33674622, 2021). "Together, inhibition of FGF19/FGFR4 signaling may play a role in the anti-tumor effects of MKIs against HCC." (PMID 33674622, 2021). "In contrast to UC tumor specimens, phosphorylation of members of the FGFR family of RTKs was lower in UC cell lines (FGFR1 25%, FGFR2 25%, FGFR3 25%, and FGFR4 0%) which may reflect the presence of stromal cells within the primary tumor samples evaluated." (PMID 34600548, 2021). "In two models (with PIK3Ca mutation and FGFR4 amplification), monotherapies decreased tumor growth without inducing regression." (PMID 32087759, 2020). "Selective FGFR4 targeting has been shown to reduce adverse effects, and the simultaneous targeting of FGFR4 and other receptor tyrosine kinases (RTKs) has been shown to indirectly enhance anti-tumor activity through normalization of the tumor microenvironment." (PMID 32154250, 2020). "If we performed a biopsy of the tumor at right portal vein transection operation, we might be able to evaluate the FGFR4 level of the tumor." (PMID 33301055, 2020). "Therefore, FGFR4-targeted liposomal formulations represent a specific drug-delivery platform for FGFR4 overexpressing RMS tumor cells, characterized by their rapid and specific receptor-mediated intracellular uptake." (PMID 33182650, 2020). "Evidence also shows downregulation of the FGF19/FGFR4 pathway could lead to decreased viability, invasion, and tumor formation of HCC in SCID mice." (PMID 32313144, 2020). "In the Rhabdomyosarcoma (RMS), mutations in FGFR4 tyrosine kinase domain (K535 and E550) might activate STAT3 signaling, increasing tumor growth and metastatic potential in mice model." (PMID 32154250, 2020). "FGF401 induces tumor regression in high FGF19-expressing HCC models by modulating FGF19/FGFR-4 signaling, inhibiting proliferation, inducing apoptosis, and inhibiting hypoxia via blood vessel normalization, and this effect was further enhanced by the addition of vinorelbine." (PMID 33235319, 2020). "We could show that FGFR4-targeted liposomes have the potential to deliver drugs specifically to FGFR4-positive tumor cells and that chimeric antigen receptor T cells built with the selected antibodies can kill specifically FGFR4-expressing RMS cells." (PMID 33182650, 2020). "Furthermore, this is the first study comparing the expression of FGF8, FGF18, and FGFR4 in tumor tissue available before and after neoadjuvant treatment." (PMID 31527546, 2019).
tumor (continued). "Instead, FGFR4 overexpression may represent a long-term signaling adaption in tumor cells following endocrine therapy." (PMID 31263748, 2019). "FGF19/FGFR4 inhibition is thought to lead to anti-tumor activities." (PMID 31167419, 2019). "Next, we analyzed the genotype frequencies of all four FGFR4 SNPs and their association to the clinicopathological characteristics of UCC patients involving whole tumor stage, primary tumor size, lymph node involvement, existence of metastasis, and the degree of histopathologic grading." (PMID 31878098, 2019). "Besides FGF8, FGF18, and FGFR4 the factors age, gender, tumor differentiation, UICC stage, lymph node ratio, adjuvant treatment, and Mandard regression grade (in neoadjuvantly treated patients only) were included." (PMID 31527546, 2019). "In contrast, genetic ablation of Fgfr4 eliminated FGF19-induced tumor formation." (PMID 30679232, 2019). "Silencing of the PPAR-α and CD36 genes significantly attenuated the FFA induced EpCAM, β-catenin and cyclinD1, further confirmed that FFA and FGF15/FGFR4 signaling could play a critical role in contributing to tumor-initiation and the development of HCC." (PMID 29973237, 2018). "N-cadherin downregulation decreased the clonogenicity and soft agar colony formation compared to the FGFR4-388Arg-overexpressing cell line and the empty vector control cell line, and the same effects were reported in vivo in tumor growth of xenografts in inmunodeprived mice with these cell lines." (PMID 29402970, 2018). "In contrast, previously published studies in the context of NSCLC considered only the FGFR4 allelic variant, not gene expression, in the tumor." (PMID 29402970, 2018). "However, the liver-enriched receptor FGFR4 is also thought to mediate the tumorigenic effects of FGF19, since inactivation of FGFR4 via gene knockout or a neutralizing antibody reduces the tumour burden in FGF19 transgenic mice." (PMID 28508871, 2017). "Analysis with regard to the pre-treatment or post-treatment tumor stage revealed a tentative association with FGFR4 levels that did not achieve statistical significance." (PMID 27650548, 2016). "Importantly, FGFR4/FGF19 co-expression was associated with AKT phosphorylation (P < 0.001), Ki-67 staining (P = 0.005) and higher tumor stage (P < 0.001)." (PMID 27192118, 2016). "In summary, our data suggest that overexpression of FGFR4 induced radioresistance by promoting resolution of radiation-induced strand breaks and tumor cell survival exclusively in the mismatch repair-proficient CRC cells but not the mismatch repair-deficient ones." (PMID 27650548, 2016). "Open trials with FGF19 and FGFR4 inhibitors in various tumours." (PMID 28943626, 2015). "In our study, we observed that FGFR4 SNPs appeared to modulate tumor progression without the presence of any significant risk factors in HCC." (PMID 25860955, 2015). "It appears that a subset of tumours is driven by the FGF19/FGFR4 pathway and these patients could benefit from treatment with FGFR4 inhibitors." (PMID 28943626, 2015). "We reported that FGFR4 SNPs appeared to modulate tumor progression without major cancer risk factors in HCC." (PMID 25860955, 2015). "Importantly, analysis of 20 human BC samples revealed a five- to tenfold increase in the expression of FGFR1 to FGFR4 in tumor tissue as compared to matched normal tissue." (PMID 24618085, 2014). "It is interesting to note that the in vitro data shows ponatinib to be effective against wild-type and mutant FGFR4, whereas our in vivo results show that ponatinib only inhibits tumor growth of cells harboring the FGFR4 mutations but not the wild-type FGFR4." (PMID 24124571, 2013). "Finally, we injected scrambled and silenced SW480 and SW48 cells subcutaneously in nude mice to analyze the effect of FGFR4 silencing on tumor growth." (PMID 23696849, 2013). "Moreover, FGFR4 knock-down cells displayed a reduced capacity for in vivo tumor formation and angiogenesis in nude mice." (PMID 23696849, 2013).
tumor (continued). "Tumor development was significantly slower in mice injected with FGFR4-silenced SW48 cells." (PMID 23696849, 2013). "The relevance of FGFR4 in tumor growth was supported by two different strategies." (PMID 23696849, 2013). "Furthermore, it has been previously demonstrated that ectopic expression of FGF19 (i.e. FGFR4-specific ligand) in mice promotes hepatocyte proliferation, hepatocellular dysplasia, and neoplasia." (PMID 22615798, 2012). "Furthermore, ectopic expression of FGF19 (i.e. FGFR4-specific ligand) in mice promotes hepatocyte proliferation, hepatocellular dysplasia, and neoplasia and FGF19-induced hepatocyte proliferation has been reported to be uniquely mediated by FGFR4." (PMID 22615798, 2012). "We demonstrate here that FGFR4 is required for FGF19-mediated liver tumorigenesis in vivo and show that treatment with an FGFR4 neutralizing antibody inhibited FGFR4-mediated signaling, proliferation, and colony formation in cell-based assays and tumor growth in preclinical models of HCC in vivo." (PMID 22615798, 2012). "Recently, FGFR4 was characterized as a regulator of RMS tumor growth and metastasis." (PMID 21253475, 2011). "The notion that germline variation in FGFR4 may influence biology of tumours is an attractive postulate." (PMID 17519899, 2007). "With respect to the UICC and AJCC TNM staging systems a significant association was found between FGFR4 protein expression and pTNM tumour stages III and IV as opposed to tumour stages I and II (UICC, P=0.023 and AJCC P=0.046)." (PMID 16721364, 2006). "Similarly, the proliferation marker Ki-67 was increased in FGFR4-positive tumours compared to FGFR4-negative tumours." (PMID 16721364, 2006). "FGFR4 expression was not noted to be associated with tumour stage, serum PSA or the presence of bony metastases." (PMID 15655558, 2005). "A significant positive correlation between FGFR4 expression and Gleason score was noted: Gleason score 7–10 tumours compared to BPH (P<0.0001, Fisher's exact test), Gleason score 4–6 tumours compared to BPH (P<0.0004), and Gleason 7–10 compared to Gleason 4–6 tumours (P<0.005)." (PMID 15655558, 2005). "In addition, FGFR4 can affect the TME, particularly CAFs; however, crosstalk between tumor–TME network functions in the context of the FGFR4 signaling pathway remains unclear." (PMID 40447617, 2025). "Furthermore, lenvatinib was also found to regulate pathways modulating antitumor immunity, including the reduction of tumor PD-L1 expression levels and Treg differentiation by blocking Fibroblast growth factor receptor-4 (FGFR4) and reducing the Treg proportion via TGF-b pathway inhibition." (PMID 40129919, 2025). "Additionally, the role of FGFR4 may vary across different tumor types or cell contexts, which could explain why its impact on glycolysis inhibition is less pronounced than that of metformin." (PMID 40091020, 2025). "In addition, ABSK-011, an FGFR4 small molecule inhibitor, may ameliorate the crosstalk between receptor tyrosine kinases and promote tumor vascular normalization." (PMID 38728500, 2024). "Since an increased expression and FGFR4 in the tumor tissues predicts a poor prognosis in various cancers and its targeting has proven promising in the treatment of FGFR4-mediated tumors, understanding molecular mechanisms that regulate FGFR4 expression in GC might be of therapeutic relevance." (PMID 37945798, 2024). "In addition, lenvatinib reactivates interferon-gamma signaling in tumor cells by inhibiting fibroblast growth factor receptor (FGFR) and enhances its combined antitumor activity with anti-PD-1 antibodies by blocking FGFR4 to reduce tumor PD-L1 levels and Treg differentiation." (PMID 37916160, 2023). "However, the transforming potential of WT FGFR4 was not as aggressive as FGFR4-activating mutations, and most WT FGFR4 tumours lacked RMS-specific immunohistochemistry markers." (PMID 37130917, 2023).
tumor (continued). "Therefore, only when FGFR4 and EZH2 signaling were simultaneously suppressed would YAP expression decline dramatically and ultimately synergistically cause massive apoptosis in tumor cells." (PMID 37085881, 2023). "Indeed, dosing at a higher frequency, or dosing over the weekends to increase exposure to the drug, may increase the inhibition of FGFR4 signaling and suppress tumor growth." (PMID 37627061, 2023). "In addition, we only confirmed the impact of FGFR4 on tumor cells at the current stage." (PMID 35562334, 2022). "Additionally, genetic defects against FGFR4 prevented transgenic mice from growing tumours." (PMID 34452553, 2021). "We performed DNA methylation analysis of the encoding genes FGFR1, FGFR2, FGFR3, FGFR4, FGF1-14, FGF16-23, and CCND1 at single CpG site resolution (840 CpG sites) employing The Cancer Genome Research Atlas (TCGA) HNSCC cohort comprising N = 530 tumor tissue and N = 50 normal adjacent tissue samples." (PMID 34933671, 2021). "Specifically, variant FGFR4-c.1162G>A predisposes individuals to a significantly accelerated progression of this pathology, while NF1-c.1915C>T negatively alters the encoded protein and should be further investigated to clarify the role of this variant in this neoplasia." (PMID 33231602, 2020). "The FGFR4 mutation could not be detected in three spatially separated samples of the primary tumour, even with high depth validation sequencing, although this does not rule out very low prevalence subclones at the time of diagnosis." (PMID 28027312, 2016). "Somatic mutations occurring before and after chromosome aneuploidy events had distinct VAF values, which allowed inference of the timing of two candidate driver mutations in this tumor, the nonsynonymous mutation of FGFR4 V550L and the nonsynonymous mutation of KRAS codon G12." (PMID 25768946, 2015). "Therefore a higher inhibitory dosage than what was used may be necessary for the treatment of wild-type FGFR4 in order to observe an effect on tumor xenograft growth." (PMID 24124571, 2013). "Finally, we demonstrated that FGFR4 targeting was able to block tumor growth in vitro and in vivo." (PMID 23696849, 2013). "Thus the FGFR4 deficiency has no direct and significant effect on tumor-associated levels of the EGFR family members Her1 and 2, two of which likely underlie the TGFα-driven tumors." (PMID 24279986, 2013). "However, no strong association between the FGFR4 genotype and indicators for the aggressive tumour was found in our study population because of potential selection bias." (PMID 17088904, 2006). "In the context of LSQ, FGF19 binding to FGFR4 can also promote the expression of vascular endothelial growth factor (VEGF), increasing tumor vascular density and creating favorable conditions for tumor cell proliferation and metastasis." (PMID 41328353, 2026). "In tumor cells, it has been demonstrated that FGF19 can activate downstream signaling pathways, including the FGFR4-ERK pathway, to promote the expression of key enzymes involved in fatty acid synthesis, such as FASN and ACC." (PMID 41328353, 2026). "Beyond direct tumor growth inhibition, LD1 also regulates gene expression by upregulating CYP7A1 and downregulating c-Fos (FOS), genes closely related to FGFR4 activity." (PMID 41328353, 2026). "Given its key role in amino acid metabolism and tumor development, the FGF19 signaling pathway, particularly FGFR4, has been regarded as a potential therapeutic target." (PMID 41328353, 2026). "Tumor growth and progression can be driven by FGF19 overexpression in HCC through the FGF19/FGFR4 signaling pathway." (PMID 41328353, 2026). "As a monoclonal antibody targeting FGFR4, LD1 has demonstrated high efficiency and specificity in treating liver cancer, both suppressing proliferation and preventing tumor development, which suggests its potential for early intervention strategies." (PMID 41328353, 2026).
tumor (continued). "FGFR3 was positive in the molecular layer of the cerebellar cortex and tumor cells, while FGFR2 was positive in tumor cells, glial cells, and blood vessels, and FGFR4 was positive in tumor cells, astrocytes, and blood vessels." (PMID 40393028, 2025). "Other potential limitations include assessing for pLoF in oncogenic candidates such as RET, ROS1, FGFR4, and MYC, while FAT1 and LEF1 reported to oscillate between oncogenic and tumour suppressive behaviour." (PMID 41038821, 2025). "Collectively, our findings demonstrated that in tumor cell glutamine metabolism, the GLUL-mediated FGF17/FGFR4/MEK5/ERK5 signaling axis sustains redox homeostasis in the tumor microenvironment via activation of NRF2-dependent antioxidant programs." (PMID 41551579, 2025). "FGF2 then binds to fibroblast growth factor receptor 4 (FGFR4) on HCC cells, activating the ERK1 pathway to promote HCC cell proliferation and forming a positive signaling loop between tumor cells and endothelial cells." (PMID 40881702, 2025). "This study reveals FGFR4 as a key driver of lipid metabolism in CRC and demonstrates that isoliquiritigenin (ISL) effectively inhibits tumor progression by targeting the FGFR4/FASN pathway." (PMID 41210688, 2025). "We have also examined the expression of several tumor aggressiveness markers (MMP‐9, CD44, CD34, PTTG, FGFR4, Ki‐67, E‐Cadherin, and N‐Cadherin) in AF, AD, and PF tumor cells of male rat pituitaries." (PMID 41017273, 2025). "The FGF family consists of numerous ligands and receptors that contribute to various aspects of tumor biology, with FGF19 and its receptor FGFR4 emerging as key players in CRC pathogenesis." (PMID 41002393, 2025). "Cellular functional and mechanistic studies indicated that FGF17 knockdown inhibited the FGFR4/MEK5/ERK5/NRF2 signaling axis, disrupted redox balance, and suppressed EMT progression, thereby reducing tumor cell migration and invasion." (PMID 41551579, 2025). "IHC analysis supported the dual inhibition of FGFR4 and CXCR3, which reduced the number of α-SMA- and Ki-67-positive cells within the TME, suggesting attenuation of CAF differentiation and tumor proliferation." (PMID 40447617, 2025). "In conclusion, this study identifies FGFR4 as a critical driver of lipid metabolic reprogramming in CRC and demonstrates that ISL effectively inhibits this axis, suppressing tumor progression." (PMID 41210688, 2025). "This led to the discovery of 36 putative tumor-surface antigens, such as integrin beta-6 (ITGB6), fibroblast growth factor receptor-4 (FGFR4), and ectonucleotide pyrophosphatase/phosphodiesterase 1 (ENPP1)." (PMID 39755633, 2025). "Collectively, dual inhibition of FGFR4 and CXCR3 suppressed tumor growth in vivo, which was accompanied by CAF suppression and immune modulation in TME." (PMID 40447617, 2025). "Network visualization highlighted key gene hubs involved in these processes, including FBLN1, CAV1, FGFR4, and ITGB1, suggesting a possible role for TNBC epithelial cells in modulating the tumor immune microenvironment." (PMID 41595458, 2025). "In conclusion, we have shown that LIF promotes the establishment of an adaptative survival niche in the tumor microenvironment, through the over-phosphorylation of STAT3 leading to FGFR4 overexpression." (PMID 37945798, 2024). "Nevertheless, both the CD276.8HTM.BBz single CAR and FGFR4.28HTM.28z-CD276.8HTM.BBz BiCisCAR T-cells controlled tumor and significantly increased survival, with the BiCisCAR demonstrating a swifter tumor clearance." (PMID 39043633, 2024). "In contrast, both FGFR4.28HTM.BBz-CD276.8HTM.BBz and FGFR4.28HTM.28z-CD276.8HTM.BBz BiCisCARs completely eradicated tumors in all mice, and the latter showed a more rapid tumor elimination." (PMID 39043633, 2024). "Tumor growth in SOX18-induced HCC metastasis was significantly inhibited after treatment with BLU-9931, a selective FGFR4 inhibitor, which indicates the significance of FGFR4 in metastatic HCC." (PMID 39796710, 2024).